DRD2 (dopamine receptor D2)
Diseases named in the same sentence as DRD2 in open-access papers (continued):
Sharing a sentence is not in itself a finding about the gene and the disease.
tumor (126 papers, 2007 to 2026). "While overexpression of DRD2 was associated with increased proliferation and tumor growth, its deactivation led to an antiproliferative effect." (PMID 36428628, 2022). "Actually, increasing evidence shows that DRs, especially DRD2, is associated with the regulation of tumor behaviors in various cancer types, including proliferation, apoptosis, autophagy, and stemness." (PMID 35461314, 2022). "Using median composite H-scores, increasing DRD2 protein expression was significantly associated with tumor grade (p < 0.0001), stage (p < 0.0001), and serous histology (p < 0.0001)." (PMID 33557912, 2021). "DRD2 encodes a kind of dopamine receptors and represents a tumor suppressor educating M1 macrophages by the NF-κB signaling pathway." (PMID 34692538, 2021). "A decrease in the expression levels of DRD2 in NSCLC tissues in comparison to adjacent normal lung tissues was negatively associated with the tumor size and total survival." (PMID 34952904, 2021). "For anti-angiogenic treatment however, the significance of DRD2 agonists seems limited based on our results regarding expression of this receptor on tumour-associated blood vessels." (PMID 31478179, 2020). "Our study indicates a possible underlying mechanism that DRD2 and nAChR involved pathways may affect the tumor immune microenvironment, leading to the expression of PD-L1." (PMID 36072788, 2022). "Therefore, this study investigated the anticancer effects of penfluridol against RCC in vitro and in a tumor xenograft model and examined possible underlying mechanisms including DRD2." (PMID 35461314, 2022). "DRD2 loss in the pituitary might therefore also promote large somatotroph tumor formation in cats." (PMID 30620005, 2019). "DRD2 activation serves as a potent, tumor-specific vascular brake on VEGFR2 phosphorylation and paracellular permeability." (PMID 42294328, 2026). "Particular attention is given to the emerging model of tumor-derived VEGF-A inducing DRD2 expression within the tumor endothelium, establishing a reciprocal paracrine feedback loop with potential biomarker relevance." (PMID 42117522, 2026). "ONC201 and the second-generation imipridone ONC206, which targets dopamine receptor D2, are currently in phase I and II trials for several tumor types, including endometrial and neuroendocrine cancers." (PMID 41163091, 2025). "Activation of the HAT domain of p300 increased H3K18/27 acetylation, promoted DRD2 transcription, and worked synergistically with DA to exert anti-tumor effects both in vitro and in vivo." (PMID 39684198, 2024). "The DRD2 antagonist pimozide inhibits tumour growth and metastasis, indicating that DRD2 inhibitors are a potential therapeutic strategy for CRC." (PMID 38494840, 2024). "In prolactinoma management, DAs target the DRD2, which are abundantly expressed on tumor cell membranes." (PMID 39684198, 2024). "Given the high expression of DRD2 on the tumor cell membrane, DA therapies such as BRC and CAB are considered first-line treatments." (PMID 39684198, 2024). "Chronic stress promoted GBM progression and up-regulated the level of dopamine (DA) and its receptor type 2 (DRD2) in tumor tissues." (PMID 37415171, 2023). "In this tumor, both DRD2 agonists were effective in reducing PRL secretion in the cell culture media (cabergoline: −46.14 ± 1.2%; UNC9994: −33.7 ± 0.57%; both p < 0.001 vs. bas)." (PMID 37370829, 2023). "DRD2 was reported to promote malignant tumor progression by activating the oxygen-independent hypoxia-inducible factor-1α (HIF-1α) pathway in response to psychologic stress." (PMID 37584707, 2023).
tumor (continued). "The results showed that doxycycline-induced DRD2 depletion not only significantly inhibited tumor growth but also blocked the promoting effect of tumor growth induced by chronic stress." (PMID 37415171, 2023). "In gastric cancer, activated DRD2 inhibits insulin-like growth factor (IGF)-I-induced tumor cell proliferation." (PMID 37215113, 2023). "Regarding the indirect effects of dopamine on tumour development, a group of studies has indicated that DRD2 signalling is a potent inhibitor of angiogenesis in several pre-clinical cancer models." (PMID 36428964, 2022). "This is important since it would delineate the effect of different tumor-infiltrating immune cell populations with varied nAChR, DRD2 or PD-L1 expression on the prognosis." (PMID 36072788, 2022). "For instance, differential tumor infiltration of immune cells having varied expression of nAChRs or DRD2 can affect their correlation in the tumor samples." (PMID 36072788, 2022). "The direct effect of dopamine on tumour cells is supported by studies in which dopaminergic drugs targeting DRD1 and DRD2 exert therapeutic effects in preclinical cancer models by inhibiting tumour proliferation and inducing death of tumour cells." (PMID 36428964, 2022). "Among these 9 candidate targets, AGT, DRD2, IL-1B, and IL-6 were significantly increased in primary tumor compared with the normal tissues, while ALB, IL-10, and IGF1 were significantly decreased in COAD tissues." (PMID 35280511, 2022). "Our study demonstrated positive correlations among PD-L1, DRD2, and nAChR in tumor samples from 46 NSCLC patients at our institution." (PMID 36072788, 2022). "Comparison of tumor biopsies to matched normal brain tissues convincingly illustrated that DRD2 expression is significantly elevated in tumor tissues." (PMID 34503167, 2021). "The subcutaneous tumor model indicated the reduction in both volume and weight of tumors derived from DRD2-overexpressing model." (PMID 33859743, 2021). "In IHC staining, DRD2-expressing 4T1 tumor samples exited higher expression of pMLKL, the executioner of necroptosis." (PMID 33859743, 2021). "And IF staining showed that Mφ exhibited M1 phenotype after co-cultivation with DRD2-expressing tumor cell." (PMID 33859743, 2021). "DRD2 and EGFR have been found to synergistically promote GBM tumors growth, and a combined inhibition of both DRD2 and EGFR causes a synergistic tumor-killing effect in mouse GBM." (PMID 34503167, 2021). "The present study reported that there is a cell–cell contact-independent mechanism of PD-L1 expression in GBM underlying the interaction between GBM and TAMs, and DRD2 is involved in modulating the PD-L1 induction between GBM and its tumor microenvironment." (PMID 34503167, 2021). "When DRD2 located in cellular membrane, it exerted anti-tumor effects through downregulating DDX5 and eEF1A2." (PMID 33859743, 2021). "DRD2 has been shown to regulate many aspects of tumor behavior, including invasion and migration in cancer cells." (PMID 33557912, 2021). "Preclinical research demonstrated that dopamine inhibits tumour angiogenesis via activation of DRD2." (PMID 31478179, 2020). "This is supported by our data showing the anti-tumor effect of ONC206 is partially abrogated in DRD2-KO cells." (PMID 32867127, 2020). "Dopamine receptor type 2 (DRD2) represents the principle target for pharmacological therapy with dopamine agonists (DAs) due to its ability to induce tumor mass shrinkage and to regulate excessive hormone secretion in prolactin (PRL)-secreting PitNETs." (PMID 33664708, 2020). "We demonstrated that inhibiting p38MAPK/ERK signaling pathway, and suppressing both glycolysis and oxidative phosphorylation (OXPHOS) in USC through antagonizing DRD2 is one of the potential mechanisms for the anti-tumor effect of ONC206." (PMID 32867127, 2020).
tumor (continued). "To further determine if the tumor-suppressive effect of ONC206 is mostly due to DRD2 antagonism, we examined the effect of DRD2 knockout on metabolic reprogramming and OXPHOS in USC cells." (PMID 32867127, 2020). "Critical outstanding questions surrounding the potential use of DRD2-targeting antipsychotics in cancer are the identification of tumor types in which these drugs will be most effective and determining how tumor-expressed dopamine receptors are activated." (PMID 31822725, 2019). "They found that in the subset of NFPTs in which DRD2 or SSTR2 agonists inhibited bulk tumor cell proliferation, the antiproliferative effect was maintained in the corresponding spheres." (PMID 31708878, 2019). "On the other hand, DRD2 showed significantly higher methylation in the control cases when compared to the tumor cases (p = 0.0002)." (PMID 30204798, 2018). "Plasma PK at 2 hours post-dose was 2.6 ug/mL, serum prolactin induction was observed as a surrogate marker of target engagement, and DRD2 was expressed in all evaluated archival tumor specimens." (PMID 29108308, 2017). "Archival tumor specimens were available for 15/17 patients and all evaluated samples exhibited expression of DRD2." (PMID 29108308, 2017). "Increased expression of SOX2 protein was also found in the tumor-bearing pituitary of the dopamine receptor D2 knock-out (Drd2−/−) mouse model." (PMID 29255445, 2017). "Blocking the DRD2 pathway inhibits the self‐renewal and survival signals of tumor stem cells." (PMID 41583906, 2026). "Stemming from these unbiased screens, as well as a growing body of literature suggesting D2Rs can function as tumor promoters, DRD2 antagonists have been investigated for efficacy in cancer treatment, and multiple D2R antagonists are currently in clinical trials." (PMID 38572507, 2024). "Tumor size showed a negative association with the DRD2 long isoform (Pearson’s r = -0.25, p = 0.05)." (PMID 37033229, 2023). "Consistently, DRD2 depletion extended the survival time of tumor-bearing chronic stressed mice." (PMID 37415171, 2023). "Interestingly, targeting DRD2 by antagonists significantly reduces the viability of cancer cells and slows tumor growth in vivo in OC pre-clinical models." (PMID 35372029, 2022). "It was also reported that the DRD2 agonists could exert anti-tumor effects through ROCK-mediated inactivation of Cofilin-1 or inhibiting EGFR/AKT/MMP-13 pathway." (PMID 35463319, 2022). "However, there are little research related to the effect of DRD3 in HCC cancer progression, while numerous studies about the carcinogenesis of DRD1 and DRD2 have been published, and tumor-related research on DRD3 is rare." (PMID 36456906, 2022). "DRD2, a tumor suppressor, encourages M1 macrophages and limits NF-B signaling to cause pyroptosis." (PMID 36119049, 2022). "Surprisingly, the nAChRs correlated with DRD2 or PD-L1 are different between our study and TCGA database, but the difference may be attributed to the difference in stages, patient population, or tumor-infiltrating immune cells." (PMID 36072788, 2022). "Taken together, this study newly manifested the regulatory mechanisms of DRD2-mediated tumor suppressive effects and may contribute to the improvement of DRD2-based prognosis prediction and anticancer therapy." (PMID 33859743, 2021). "Ectopic expression of DRD2 inhibited tumor cell growth as evidenced by CCK8 assay." (PMID 33859743, 2021). "The tumor-suppressive effects of DRD2 were further determined in vivo." (PMID 33859743, 2021). "In addition, the expression of DRD2 and PD-L1 in GBM modulates tumor-associated macrophage polarization." (PMID 34503167, 2021). "Subcutaneous tumor model was used to explore DRD2 effects in vivo." (PMID 33859743, 2021). "Furthermore, the ectopic expression of DDX5 and eEF1A2 also weakened the inhibitory effects of DRD2 on tumor proliferation as assessed by CCK8 and Transwell® assay." (PMID 33859743, 2021).
tumor (continued). "NF-κB signaling plays diverse and complex role in tumors 63, and DRD2 might mediate this signaling to exert anti-tumor effects." (PMID 33859743, 2021). "This study also identified the tumor-suppressive effect of DRD2 in vitro and in vivo." (PMID 33859743, 2021). "Dependent on tumour type and DRD2 expression on tumour cells, treatment with a DRD2 agonist or antagonist may have anti-tumour activity." (PMID 31478179, 2020). "Because ONC201 has been shown to bind to and selectively antagonize DRD2, we hypothesized that the tumor-suppressive effects of ONC206 are also mediated by DRD2." (PMID 32867127, 2020). "In our study however, we observed low or absent DRD2 protein expression on tumour-associated endothelial cells." (PMID 31478179, 2020). "Knockout experiments demonstrated a DRD2-dependent anti-tumor effect of ONC206." (PMID 32867127, 2020). "Compared with the DRD2−/− mice, the plasma PRL levels in the peripheral blood (P < 0.01) and PRL mRNA expression levels in the pituitary gland (P < 0.05) were decreased, and the tumor/body weight ratio (P < 0.001) was decreased significantly in the DRD2−/−MAPK14+/− mice." (PMID 32894113, 2020). "DRD2 is a G protein-coupled receptor that promotes tumor growth." (PMID 33204317, 2020). "We first determined the effect of DRD2 silencing on the tumor-suppressor effect of ONC206." (PMID 32867127, 2020). "If DRD2 can promote self-renewal in human tumors, it is important to determine whether dopamine is present in the tumor and/or tumor microenvironment." (PMID 31822725, 2019). "Interestingly, in agreement with human tumor data, DRD2 mRNA expression is, on average, elevated in basal-like cell lines." (PMID 31822725, 2019). "Since dopamine has been observed in these immune cells that have important functions within the tumor microenvironment, they could be a source of dopamine in vivo, helping to support the self-renewal of tumor cells that express DRD2." (PMID 31822725, 2019). "The anticancer activity of JX57, a derivative of the dopamine receptor D2 antagonist CPZ, could result from its effects on the nervous system and tumor associations; however, in this study, only the direct target of action on tumor cells was assessed, representing a limitation of the study." (PMID 38342610, 2024). "Dopamine has also been identified as an important phenylalanine-derived metabolite in tumor microenvironment, which was found to either promote or inhibit tumor cell growth through different receptor-mediated signaling pathways (e.g., G protein-coupled dopamine D2 receptor (DRD2))." (PMID 39115570, 2024). "DRD2 might restrict NF-κB signaling to regulate anti-tumor effects." (PMID 33859743, 2021). "In the tumor microenvironment, VEGF-A selectively induces endothelial DRD2 expression through specific transcriptional mechanisms - a molecular signature that is absent in quiescent normal vasculature." (PMID 42294328, 2026). "DA influences tumor behavior via its receptors, categorized as D1-like (DRD1, DRD5) and D2-like (DRD2, DRD3, DRD4), which vary in tumor expression and function." (PMID 40456735, 2025). "In this study, we identified a new signaling regulatory mechanism, namely the DRD2/ERK/β-catenin pathway and Dopamine/ERK/TH regulatory loop, which was activated by chronic stress and in turn promoted tumor progression." (PMID 37415171, 2023). "Considering all the models, a patient stratification based on the extrasellar growth of the tumor, sex, age and the expression of E-cadherin, GHRL, IN1-GHRL, DRD2, SSTR5 and PEBP1 is proposed, with accuracies that stand between 71 to 95%." (PMID 35643771, 2022). "In breast cancer, DRD2 promotes M1 polarization of macrophages and triggers GSDME-executed pyroptosis that regulates the tumor microenvironment and inhibits tumor malignant progression." (PMID 35958626, 2022).
tumor (continued). "Taking ONC201 as an example, as a dopamine receptor D2 (DRD2) antagonist, it inactivates protein kinase B/extracellular-regulated protein kinases (AKT/ERK) signaling in tumor cells." (PMID 36010960, 2022). "Both DRD2 and DRD4 have significantly higher expression in the non-tumor samples than the GBM samples, while DRD3 has similar expression between GBM and non-tumor." (PMID 33945569, 2021). "In the regulatory mechanism, loading-driven dopamine exerts its tumor-suppressing effect via DRD1, while the effects of FP are mediated via DRD2." (PMID 34031366, 2021). "The present study aims to investigate the molecular mechanisms underlying GBM and monocytes/macrophage interaction, as well as how DRD2 modulates PD-L1 induction within GBM and tumor microenvironment." (PMID 34503167, 2021). "To determine the tumor-suppressing mechanism induced by loading-driven dopamine increases, we focused on two dopamine receptors, DRD1 and DRD2, as representatives of types D1 and D2, respectively." (PMID 34031366, 2021). "The results showed that blockade of MAPK14 expression in the mice significantly reduced tumor formation in the pituitary gland, and thus PRL production and secretion in estradiol-induced and DRD2−/− prolactinoma." (PMID 32894113, 2020). "Meanwhile, Control-KO cells showed a similar response to that of the parental ARK2 cells, suggesting that DRD2 mediates the tumor-suppressor effect of ONC206 and USC cells expressing higher levels of DRD2 are more sensitive to ONC206." (PMID 32867127, 2020). "They found that DRD2 interacted with von Hippel-Lindau (VHL) in the nucleus, and competitive binding of DRD2 and HIF-1α to VHL resulted in reduced ubiquitination-mediated degradation of HIF-1α, enhancing the epithelial-mesenchymal transition of tumor cells." (PMID 37415171, 2023). "Future in vitro and in vivo studies are warranted to determine whether mentioned drugs (such as DRD2 antagonists, MAPK12 inhibitors, RET inhibitors, or drugs targeting PTN) can inhibit tumor growth and improve survival and quality of life in dogs with PPGL." (PMID 37691636, 2023). "In tumoral lactotrophs and NF-PitNETs, the lack of β-arrestin 2 prevents the inhibitory effect of DRD2 on AKT, with a consequent resistance to the antimitotic action of DAs." (PMID 37370829, 2023). "In tumoral lactotrophs and NF-PitNETs, the lack of β-arrestin 2 prevents the inhibitory effect of DRD2 on AKT pathway activation with a consequent resistance to the antimitotic action of DAs." (PMID 35721701, 2022). "Further IHC-P staining has discovered the co-expression of DRD5 but not DRD2 with TH in EC tumor samples." (PMID 33898321, 2021). "In PitNETs expressing DRD2, modulation of P-FLNA might suggest new pharmacological strategies to overcome drug resistance, and P-FLNA might represent a new biomarker for tumor responsiveness to dopaminergic agents." (PMID 33664708, 2020). "The actin binding protein filamin A (FLNA) is required for somatostatin receptor 2 (SSTR2) and dopamine receptor 2 (DRD2) expression and signaling in GH- and PRL-secreting PitNETs, respectively, playing a role in tumor responsiveness to somatostatin receptors ligands and dopaminergic drugs." (PMID 33664708, 2020). "Interestingly, the expression of pituitary tumor-specific receptors, SS receptors type 2 (SSTR2) and 5 (SSTR5) or DRD2 has been detected in cells in the spheres." (PMID 31708878, 2019). "The DRD2 inverse agonist and antipsychotic haloperidol improved the efficacy of an epidermal growth factor receptor inhibitor, although haloperidol (which also has efficacy in the nanomolar range on DRD3, DRD4, and several other receptors) was insufficient to decrease tumor growth alone." (PMID 33945569, 2021).